AQP12A (aquaporin 12A)
Description:
Putative aquaporin. Could form homotetrameric transmembrane channels, with each monomer independently mediating water transport across the plasma membrane along its osmotic gradient.
Synonyms: AQP-12; AQP12; AQPX2
Tractability: Antibody: UniProt predicts a signal peptide or a membrane-spanning region.
Gene: Protein-coding gene on chromosome 2 (240,691,866 to 240,698,483, forward strand). Ensembl gene ENSG00000184945.
Subcellular location: Membrane
Pathways (Reactome):
Transport of small molecules: Passive transport by Aquaporins
Gene Ontology:
Molecular function: water channel activity; channel activity
Biological process: intracellular water homeostasis; transmembrane transport; water transport
Cellular component: plasma membrane; membrane
Genetic constraint (gnomAD): Loss-of-function variants: 11 observed, 9.12 expected, observed/expected ratio (o/e) 1.21, 90% interval 0.75 to 1.83. That is too few expected variants to judge how well the gene tolerates losing a copy. Missense variants: 197 observed, 200.3 expected, observed/expected ratio (o/e) 0.98, 90% interval 0.88 to 1.11. Synonymous variants: 99 observed, 94.69 expected, observed/expected ratio (o/e) 1.05, 90% interval 0.89 to 1.24.
Homologues: Orthologues: chimpanzee AQP12B (97% identical), macaque AQP12 (91% identical), mouse Aqp12 (70% identical), rat Aqp12a (69% identical), dog AQP12 (67% identical), zebrafish aqp12 (36% identical), Drosophila melanogaster AQP (22% identical), Caenorhabditis elegans aqp-10 (19% identical), Caenorhabditis elegans aqp-9 (19% identical), Caenorhabditis elegans aqp-11 (17% identical). Paralogues in human: AQP12B (99% identical), AQP11 (24% identical).
Diseases named in the same sentence as AQP12A in open-access papers:
AQP12A is named in the same sentence as 9 diseases in open-access papers, as found by Europe PMC text mining. Sharing a sentence is not in itself a finding about the gene and the disease. The quoted sentences say what the papers report.
cancer (1 paper, 2015). A tumor composed of atypical neoplastic, often pleomorphic cells that invade other tissues. "In patient S2 we observed a T129M in AQP12A, which is not predicted to alter protein function, and this gene has not been implicated in cancer." (PMID 26497854, 2015).
AQP12A also shares sentences with these, for which no sentence is quoted: pancreatitis (3 papers); acute pancreatitis (1); avian influenza (1); Constipation (1); Insulin resistance (1); kidney cancer (1); neuroblastoma (1); Spastic paraplegia (1).